CMKLR1 (chemerin chemokine-like receptor 1)
Description:
Receptor for the chemoattractant adipokine chemerin/RARRES2 and for the omega-3 fatty acid derived molecule resolvin E1. Interaction with RARRES2 initiates activation of G proteins G(i)/G(o) and beta-arrestin pathways inducing cellular responses via second messenger pathways such as intracellular calcium mobilization, phosphorylation of MAP kinases MAPK1/MAPK3 (ERK1/2), TYRO3, MAPK14/P38MAPK and PI3K leading to multifunctional effects, like reduction of immune responses, enhancing of adipogenesis and angionesis. Resolvin E1 down-regulates cytokine production in macrophages by reducing the activation of MAPK1/3 (ERK1/2) and NF-kappa-B. Positively regulates adipogenesis and adipocyte metabolism. (Microbial infection) Acts as a coreceptor for several SIV strains (SIVMAC316, SIVMAC239, SIVMACL7E-FR and SIVSM62A), as well as a primary HIV-1 strain (92UG024-2).
Synonyms: CHEMR23; DEZ; RVER1; ERV1; CHEMERINR
Tractability: Small molecule: a structure with a bound ligand is known; a high-quality ligand is known; it belongs to a druggable protein family. Antibody: UniProt places it where antibodies can reach, with high confidence; its Gene Ontology location is reachable by antibodies, with high confidence; UniProt predicts a signal peptide or a membrane-spanning region. PROTAC: a small molecule that binds it is known.
Target class: Membrane receptor; Chemerin receptor; Peptide receptor (family A GPCR); Chemokine receptor-like; Family A G protein-coupled receptor
Gene: Protein-coding gene on chromosome 12 (108,288,044 to 108,339,317, reverse strand). Ensembl gene ENSG00000174600.
Subcellular location: Cell membrane
Pathways (Reactome):
Signal Transduction: Class A/1 (Rhodopsin-like receptors)
Gene Ontology:
Molecular function: adipokinetic hormone binding; adipokinetic hormone receptor activity; protein binding; chemokine receptor activity; complement receptor activity; G protein-coupled receptor activity; signaling receptor activity
Biological process: chemotaxis; G protein-coupled receptor signaling pathway; positive regulation of macrophage chemotaxis; regulation of calcium-mediated signaling; complement receptor mediated signaling pathway; immune response; inflammatory response; negative regulation of interleukin-12 production; phospholipase C-activating G protein-coupled receptor signaling pathway; positive regulation of cold-induced thermogenesis; positive regulation of cytosolic calcium ion concentration; positive regulation of fat cell differentiation; regulation of inflammatory response; skeletal system development; chemokine-mediated signaling pathway; signal transduction
Cellular component: plasma membrane; G protein-coupled receptor complex; membrane
Genetic constraint (gnomAD): Loss-of-function variants: 6 observed, 8.64 expected, observed/expected ratio (o/e) 0.69, 90% interval 0.38 to 1.36. That is too few expected variants to judge how well the gene tolerates losing a copy. Missense variants: 429 observed, 504.49 expected, observed/expected ratio (o/e) 0.85, 90% interval 0.79 to 0.92. Synonymous variants: 178 observed, 191.97 expected, observed/expected ratio (o/e) 0.93, 90% interval 0.82 to 1.05.
Homologues: Orthologues: chimpanzee CMKLR1 (99% identical), macaque CMKLR1 (98% identical), rabbit CMKLR1 (88% identical), pig CMKLR1 (86% identical), dog CMKLR1 (84% identical), guinea pig CMKLR1 (84% identical), rat Cmklr1 (82% identical), mouse Cmklr1 (80% identical), tropical clawed frog cmklr1 (49% identical), zebrafish cmklr1 (35% identical), zebrafish cmklr1l1 (30% identical), zebrafish cmklrl2 (27% identical). Paralogues in human: C3AR1 (34% identical), FPR1 (32% identical), FPR2 (32% identical), FPR3 (31% identical), C5AR1 (31% identical), GPR33 (31% identical), GPR32 (29% identical), C5AR2 (25% identical).
Diseases named in the same sentence as CMKLR1 in open-access papers:
CMKLR1 is named in the same sentence as 164 diseases in open-access papers, as found by Europe PMC text mining. Sharing a sentence is not in itself a finding about the gene and the disease. The quoted sentences say what the papers report.
Obesity (45 papers, 2011 to 2025). Accumulation of substantial excess body fat. "Nevertheless, our findings underlie a potential therapeutic feature of CMKLR1 in obesity and the associated metabolic diseases from the thermogenic viewpoint of beige fat." (PMID 38933207, 2024). "Chemerin is an obesity-associated adipokine and is involved in various processes including inflammation by interacting with chemokine-like receptor 1 (CMKLR1)." (PMID 38532900, 2024). "Accordingly, CMKLR1 deficiency protects mice from HFD-induced obesity, AT inflammation, and insulin resistance." (PMID 35909571, 2022). "Of note, the hepatic expression of both chemerin and CMKLR1 was associated with obesity, which can partially explain the inconsistency of the results." (PMID 36009862, 2022). "Chemerin and its receptor CMKLR1 are both expressed in adipose tissue, and they have been reported to be augmented in obesity and IR states (T2DM), decreasing after weight loss." (PMID 36009862, 2022). "The RARRES2/CMKLR1 system is considered to be a potential actor underlying the regulation of glucose and fat metabolism linked to obesity in humans and mice." (PMID 30777067, 2019). "The vital roles of chemerin/CMKLR1 on disorders of glycolipid metabolism including IR and obesity associated inflammation were demonstrated by knockout mice deficiency in chemerin or CMKLR1." (PMID 30873215, 2019). "Given the association of chemerin with obesity and related diseases, we decided to study in detail the regulation of chemerin and CMKLR1 expression in white adipose tissue (WAT)." (PMID 30257454, 2018). "The implications of CMKLR1 in obesity increase the risk of these patients developing cardiovascular disease." (PMID 29279348, 2018). "The chemerin/CMKLR1 axis is involved in immunity and inflammation, and it has also been implicated in obesity and cancer." (PMID 29221117, 2017). "The chemerin-CMKLR1 axis regulates lipid and glucose metabolism, and is associated with chronic inflammation, obesity, and obesity-related disorders such as insulin resistance and metabolic syndrome, with several compounds and antibodies under preclinical or early clinical investigation." (PMID 39752296, 2025). "As it is already known that chemerin levels are increased in obesity, further research outlined the regulation of adipogenesis, inflammation and vascular dysfunction along with its cell surface receptor chemR23, encoded by the CMKLR1-gene." (PMID 37239098, 2023). "This is the first study that links the increment of CMKLR1 expression with insulin production, showing an association with fat mass and corporal dimensions, while the increased serum levels of chemerin in obesity were observed, favoring a dysmetabolic response." (PMID 27239101, 2016). "Given the etiological significance of identifying signaling pathways that induce beige fat and restore obesity-linked dysfunction in adipose tissue, our findings indicate that modulation of the intracellular signaling of CMKLR1 may be a potentially novel therapeutic strategy." (PMID 38933207, 2024). "Obesity also alters chemerin receptor signaling; chemerin and CMKLR1 expression in PVAT are approximately twofold higher in HFD-fed rats than in controls." (PMID 40514684, 2025). "In previous reports, mice deficient in CMKLR1 showed attenuated androgen-induced lipid accumulation, which suggests an anti-obesity role of CMKLR1 by regulating lipid accumulation." (PMID 38933207, 2024). "Collectively, the expression profiles and biological effects of CMKLR1 imply important roles of CMKLR1 in inflammation, obesity and cancers." (PMID 39595036, 2024). "Chemokine-like receptor 1 (CMKLR1) is a receptor for chemerin, a potent adipokine that is elevated with obesity." (PMID 36437471, 2022). "This understanding is needed to develop obesity avoidance strategies or appropriate therapies, such as blocking CMKLR1 activity, to address the biggest health challenge of our time." (PMID 35711300, 2022).
Obesity (continued). "Apart from being found in different inflammatory fluids, many immune cells express CMKLR1, including dendritic cells, macrophages, monocytes, and natural killer cells, which usually infiltrate adipose tissue in obesity or the heart in pathological states." (PMID 33081064, 2020). "Deletion of the chemerin receptor gene (CMKLR1) showed a protective effect against obesity and decreased insulin secretion by reducing glucose uptake in skeletal muscle and adipose tissue." (PMID 32401924, 2020). "This argues against a co-regulation of chemerin and CMKLR1 expression in adipocytes by inflammatory mediators that contribute to insulin resistance and metabolic disease in obesity." (PMID 30841637, 2019). "The present study confirmed the enhancement of CMKLR1 in the livers and gastrocnemius of obesity and diabetes rats, suggested the possibility of CMKLR1 on the disorder of glycolipid metabolism by increasing inflammation in the lives and muscles." (PMID 30873215, 2019). "Adipocytes and stromal-vascular cells in adipose tissue express CMKLR1, and immunohistochemical approaches have to identify the cell type specific regulation of CMKLR1 in obesity." (PMID 30841637, 2019). "CMKLR1 knockout mice highlight the role of this receptor in inflammation and obesity, and similarly, GPR1 knockout mice exhibit glucose intolerance." (PMID 29279348, 2018). "In contrast, another more recent study showed that Cmklr1-knockout mice display mild obesity but normal adipocyte differentiation." (PMID 29848608, 2018). "Chemerin merges obesity with inflammation inactivating the orphan G-protein coupled receptor chemokine-like receptor 1 (CMKLR1, ChemR23) which is characteristic for cells of the innate immune system." (PMID 29849871, 2018). "Of note, while total chemerin serum levels are raised in obesity, the portion capable of activating CMKLR1 is unchanged." (PMID 28661458, 2017). "One important observation from this study is that, in the context of obesity, soluble chemerin levels enhanced both the inflammation and dysmetabolic phenotype, showing how an opposite change in the expression of CMKLR1 takes place once IR is established." (PMID 27239101, 2016). "Both male and female CMKLR1 knockout and heterozygote mice displayed a mild tendency to obesity and impaired glucose homeostasis, but only when they were fed on a high-fat died, rather than a standard low-fat diet." (PMID 25699203, 2015). "We attempted to investigate the potential of agonists of CMKLR1 in the treatment of obesity using chemerin and the C-terminal peptides described here, by following the approach used by others to demonstrate that the stable C-9 analogue is active in vivo." (PMID 25699203, 2015). "Demonstration of proof-of-concept in an animal model of type 2 diabetes and obesity clearly requires the identification of a stable compound that is more effective as an agonist of CMKLR1." (PMID 25699203, 2015). "Although chemerin is implicated in the pathogenesis of obesity-related metabolic and cardiovascular disorders, no pharmacological agents that specifically target the chemerin/CMKLR1 axis, including PVAT-derived chemerin, are currently available." (PMID 40514684, 2025). "CMKLR1 is linked to nuclear factor kappa-light-chain-enhancer of activated B cells (NF-κB) activation and insulin signaling, and kinesin family member 5B (KIF5B) is associated with insulin resistance and obesity." (PMID 37958793, 2023). "Chemerin regulates immune function, obesity, and metabolism through three receptors [chemokine-like receptor 1 (CMKLR1), G-protein-coupled receptor 1 (GPR1), C–C motif chemokine receptor-like 2 (CCRL2)] that are expressed in the hypothalamus, pituitary gland, testis, ovary, and placenta." (PMID 37964253, 2023). "Moreover, it was shown that HFD-fed CMKLR1 knockout and heterozygous mice exhibit a higher tendency to develop obesity and impaired glucose homeostasis." (PMID 35406450, 2022).
Obesity (continued). "In mesenteric adipose tissue of Psammomys obesus, CMKLR1 expression was also induced in obesity." (PMID 30841637, 2019). "The downregulation of CMKLR1 in Kupffer cells by a phosphatidyl inositol 3-kinase inhibitor improved hepatic insulin resistance and inflammation, suggesting that the chemerin–CMKLR1 signaling pathway contributes to metabolic disease in obesity by modulating the function of these immune cells." (PMID 30841637, 2019). "Besides serum chemerin, the levels of chemerin/CMKLR1 in the metabolic organs of obesity and diabetes rats were alleviated by exercise, which were likely to be associated with the improvement of glycolipid metabolism." (PMID 30873215, 2019). "Besides serum chemerin, the levels of chemerin/CMKLR1 in the metabolic organs of obesity and diabetes rats were alleviated by 4-week aerobic exercise, which were likely to be associated with the improvement of glycolipid metabolism." (PMID 30873215, 2019). "In addition, the present study first reported, to our knowledge, that 4-week aerobic exercise attenuated the levels of CMKLR1 in the livers and gastrocnemius of obesity and diabetes rats." (PMID 30873215, 2019). "Similarly, chemerin and CMKLR1 levels are higher in mice fed on a high-fat diet and mouse models of obesity." (PMID 29279348, 2018). "Therefore, the aim of this study was to characterize the inflammatory and metabolic phenotype of subjects with obesity-IR state based on the chemerin soluble levels and its receptor CMKLR1 expression." (PMID 27239101, 2016). "The findings that we report here lead, however, to a different conclusion—that chemerin, acting through CMKLR1, opposes diet-induced obesity and insulin resistance, and that therefore an agonist of CMKLR1 might be of value in the treatment of type 2 diabetes." (PMID 25699203, 2015). "To address these questions, and in particular the potential of agonists or antagonists of the chemerin receptor CMKLR1 in the treatment of type 2 diabetes and obesity, we studied the metabolic phenotypes of both male and female, CMKLR1 knockout and heterozygote mice." (PMID 25699203, 2015). "However, the co-occurrence of obesity may suppress the expression of CMKLR1 in hGCs, thus leading to a higher resistance to chemerin action." (PMID 39767764, 2024). "In addition, the chemerin–CMKLR1 axis is a physiological negative regulator of thermogenic beige fat, and targeting this pathway might be a novel strategy for obesity." (PMID 37447205, 2023). "Hence, the adipose chemerin-CMKLR1 pathway could be a potential therapeutic target for obesity-related metabolic disorders." (PMID 35909571, 2022). "Thus, chemerin–CMKLR1 signaling may enhance adipogenesis in obesity to allow for the storage of surplus lipids." (PMID 30841637, 2019). "Thus, chemerin/CMKLR1 may be promising new targets for the treatment of obesity and its related diseases, and peptides or other substances that affect chemerin/CMKLR1 axis will be used in the future in the treatment of obesity and diabetes." (PMID 30873215, 2019). "Therefore, the purpose of the current study was to verify: 1) if exercise reduced chemerin and CMKLR1in the peripheral metabolic organs (not only serum chemerin) of obesity and diabetes rats; 2) if exercise-induced decreases of chemerin/CMKLR1 were mediated by PPARγ in the diabetes rats." (PMID 30873215, 2019). "The mature-onset obesity phenotype has been observed in male but not female CMKLR1-deficient mice." (PMID 27548138, 2016). "However, continued efforts to clarify the factors that regulate adipocyte production of active chemerin are required to understand why chemerin concentrations become elevated in obesity and to better assess the functional impact of chemerin/CMKLR1 signalling in obesity related disease progression." (PMID 23227233, 2012). "During obesity, increased levels of inflammatory cytokines, such as IL-6 and TNF-α, augment CMKLR1 expression and increase monocyte attachment to endothelial cells." (PMID 40514684, 2025).
Obesity (continued). "The chemerin receptors chemokine-like receptor 1 (CMKLR1) and G protein-coupled receptor 1 (GPR1), play crucial roles in regulating obesity, inflammation, and cancer, highlighting their potential as therapeutic targets." (PMID 39752296, 2025). "Therefore, two ligands of CMKLR1 may correlate with the development of obesity." (PMID 38933207, 2024). "Elevated gene expression of chemerin and its main receptor ChemR23 (also referred as chemokine-like receptor 1, CMKLR1) are positively correlated with the severity of several diseases such as obesity, T2DM, rheumatoid arthritis and cardiovascular disease." (PMID 38074873, 2023). "During obesity, VAT-derived chemerin can recruit pDCs through CMKLR1, and neutralization of CMKLR1 abolishes chemerin-induced pDC migration." (PMID 34421909, 2021). "However, whether the levels of chemerin and CMKLR1 in peripheral metabolic organs are altered by exercise in obesity and diabetes are still unknown, not to speak of the underlying mechanism." (PMID 30873215, 2019). "In apparent contrast with this latter finding, CMKLR1 and CCRL2 knockout mice exposed to a high-fat diet developed enhanced obesity, leading the authors to suggest that the net effect of the chemerin/CMKLR1 pathway might depend on the experimental setting." (PMID 37447205, 2023). "Increased serum chemerin in obesity did not match the ex-vivo measured activation of chemokine-like receptor 1 (CMKLR1)." (PMID 33066325, 2020). "Elevated serum chemerin in obesity did not result in enhanced activation of the chemerin receptor CMKLR1." (PMID 31409008, 2019). "The CMKLR1 knockout mice have highlighted the potential role of CMKLR1 in metabolic syndrome and obesity, although findings are not consistent." (PMID 29279348, 2018). "Although the CMKLR1 mRNA level in fat tissue is not changed by obesity, the local RARRES2 mRNA expression in visceral and subcutaneous adipose tissue is significantly increased in obese individuals." (PMID 29848608, 2018). "Indeed, chemerin, GPR1 and CMKLR1 knock-out mice do not display gross hepatic abnormalities even when fed diets to produce obesity or NAFLD." (PMID 28661458, 2017). "Both CMKLR1 expression and chemerin levels were increased in obesity without IR." (PMID 27239101, 2016). "In the 12q24 area there are other genes that might be involved in the phenotype including THRAP2, TBX5 and PTPN11 for cardiac and great vessel anomalies; TBX5, CMKLR1, and TRPV4 for skeletal defects; PRKAB1, GPR109A, and GPR109B for increased hunger and obesity." (PMID 21457577, 2011).